H1-1 (H1.1 linker histone, cluster member)
Description:
Histone H1 protein binds to linker DNA between nucleosomes forming the macromolecular structure known as the chromatin fiber. Histones H1 are necessary for the condensation of nucleosome chains into higher-order structured fibers and promote formation of the H3K27me3 mark by the PRC2/EED-EZH2 complex. Also acts as a regulator of individual gene transcription through chromatin remodeling, nucleosome spacing and DNA methylation (By similarity).
Synonyms: H1F1; HIST1H1A; H1.1; H1a; HIST1
Tractability: PROTAC: ubiquitination databases record sites on it.
Gene: Protein-coding gene on chromosome 6 (26,017,032 to 26,017,787, reverse strand). Ensembl gene ENSG00000124610.
Subcellular location: Nucleus; Chromosome
Subcellular location (Human Protein Atlas): Nucleoplasm
Pathways (Reactome):
Cellular responses to stimuli: Formation of Senescence-Associated Heterochromatin Foci (SAHF)
Programmed Cell Death: Apoptosis induced DNA fragmentation
Gene Ontology:
Molecular function: chromatin DNA binding; protein binding; structural constituent of chromatin; double-stranded DNA binding; nucleosomal DNA binding; DNA binding; heparin binding
Biological process: chromosome condensation; negative regulation of DNA recombination; spermatogenesis; nucleosome assembly; positive regulation of receptor-mediated endocytosis
Cellular component: chromatin; chromosome; euchromatin; nucleoplasm; nucleus; cell surface; nucleosome; vesicle
Genetic constraint (gnomAD): Loss-of-function variants: 3 observed, 1.44 expected, observed/expected ratio (o/e) 2.08. That is too few expected variants to judge how well the gene tolerates losing a copy. Missense variants: 516 observed, 279.11 expected, observed/expected ratio (o/e) 1.85, 90% interval 1.72 to 1.97. Synonymous variants: 211 observed, 117.61 expected, observed/expected ratio (o/e) 1.79, 90% interval 1.6 to 1.96.
Homologues: Orthologues: chimpanzee H1-1 (99% identical), macaque H1-1 (91% identical), guinea pig H1-1 (82% identical), rabbit H1-1 (82% identical), dog H1-1 (81% identical), mouse H1f1 (79% identical), Caenorhabditis elegans hil-6 (24% identical), Caenorhabditis elegans hil-2 (24% identical), Caenorhabditis elegans hil-3 (24% identical), Caenorhabditis elegans hil-4 (23% identical), Caenorhabditis elegans hil-5 (22% identical). Paralogues in human: H1-4 (73% identical), H1-5 (70% identical), H1-3 (69% identical), H1-2 (67% identical), H1-6 (49% identical), H1-0 (39% identical), H1-8 (29% identical), H1-10 (27% identical), H1-7 (26% identical).
Diseases named in the same sentence as H1-1 in open-access papers:
H1-1 is named in the same sentence as 18 diseases in open-access papers, as found by Europe PMC text mining. Sharing a sentence is not in itself a finding about the gene and the disease. The quoted sentences say what the papers report.
breast carcinoma (4 papers, 2014 to 2026). "Pathway enrichment revealed associations with cell cycle regulation (E2F3, MKI67), DNA repair (BRCA2), and transcriptional control (MED1), with six priority genes (MED1, BRCA2, E2F3, PITPNB, H1-1, and FARP2) showing established breast cancer relevance." (PMID 41614924, 2026).
prostate carcinoma (4 papers, 2012 to 2025). A carcinoma that arises from epithelial cells of the prostate gland. "It is still unclear whether the same pathways are used by the restored H11/HspB8 to cause cell death in prostate cancer, Ewing sarcoma, and/or hematologic malignancies." (PMID 23056924, 2012).
melanoma (3 papers, 2012 to 2025). A malignant, usually aggressive tumor composed of atypical, neoplastic melanocytes. "The stress-related protein HSPB8 was first discovered in human melanoma cells as a kinase of the H11 protein." (PMID 37404760, 2023). "Collectively the data identify TAK1 as a central player in the H11/HspB8-induced growth arrest/death of melanoma cells and underscore the therapeutic promise of H11/HspB8." (PMID 23056924, 2012). "Consequently, H11/HspB8 is silenced in a large proportion of melanoma tissues by aberrant DNA methylation (a CpG island is present at the 5′ UTR, 216 bp upstream of the transcription start site)." (PMID 23056924, 2012).
Autoimmunity (1 paper, 2012). The occurrence of an immune reaction against the organism's own cells or tissues. "Both ICP10PK and H11/HspB8 were implicated in inflammatory processes that involve dendritic cells activation through Toll-like receptor-dependent pathways and may contribute to the onset of autoimmunity." (PMID 23056924, 2012).
glioblastoma (1 paper, 2012). The most malignant astrocytic tumor (WHO grade IV). "H11/HspB8 has antiapoptotic activity in glioblastoma and breast cancer cells through cell-cycle regulation, potentially involving activation of the growth-associated transcription factor E2F and/or the cyclin-dependent kinase cdk4." (PMID 23056924, 2012).
influenza (1 paper, 2022). An acute viral infection of the respiratory tract, occurring in isolated cases, in epidemics, or in pandemics; it is caused by serologically different strains of viruses (influenzaviruses) designated A, B, and C, has a 3-day incubation period, and usually lasts for 3 to 10 days. "To better understand how inhibition of the influenza neuraminidase (NA) protein contributes to protection against influenza, we produced lentiviral vectors pseudotyped with an avian H11 hemagglutinin (HA) and the NA of all influenza A (N1–N9) subtypes and influenza B (B/Victoria and B/Yamagata)." (PMID 36146598, 2022).
tumor (7 papers, 2012 to 2023). "Restored expression of H11/HspB8 causes growth arrest and inhibits tumor growth through the activation of programmed cell death pathways." (PMID 23056924, 2012). "The cell-cycle regulatory potential of H11/HspB8 in normal cells, its dysfunctional state in cancer cells, and its ability to induce tumor cell death upon restored expression identify H11/HspB8 as a tumor suppressor." (PMID 23056924, 2012). "Significantly, the ΔPK oncolytic activity also includes the activation of multiple programmed cell death (PCD) pathways and is accompanied by the upregulation of H11/HspB8 that functions as a tumor suppressor." (PMID 23056924, 2012). "Its restored expression induces cell death and inhibits tumor growth in xenograft models, identifying H11/HspB8 as a tumor suppressor." (PMID 23056924, 2012). "Indeed, caspase-1 cleaved the haploinsufficient tumor suppressor Beclin-1 that was also upregulated by H11/HspB8 through a TAK1/mTORC1 pathway that involved mTOR phosphorylation at S2481, which is the site of intrinsic mTORC1-specific catalytic activity." (PMID 23056924, 2012). "While H11/HspB8 has two heat-shock-factor- (HSF-) binding sites, 1,000 bases upstream of the translation initiation site, its expression is not always heat inducible and it appears to differ in tumor as compared to normal cells." (PMID 23056924, 2012).
cancer (4 papers, 2012 to 2024). A tumor composed of atypical neoplastic, often pleomorphic cells that invade other tissues. "We believe, UNIVmAb detected H11 protein, is a unique hyaluronan binding protein, that can be used as a common biomarker for all cancers." (PMID 31727145, 2019).
adenocarcinoma (1 paper, 2019). A common cancer characterized by the presence of malignant glandular cells. "We investigated the H11 antigen by proteomic analysis from grade ll adenocarcinoma of the colon." (PMID 31727145, 2019).
H1-1 also shares sentences with these, for which no sentence is quoted: schizophrenia (2 papers); benign tumor (1); bipolar disorder (1); Ewing sarcoma (1); heart failure (1); infection (1); Infertility (1); mucositis (1); prostate adenocarcinoma (1).